ITSN2 (intersectin 2)
Description:
Adapter protein that may provide indirect link between the endocytic membrane traffic and the actin assembly machinery. May regulate the formation of clathrin-coated vesicles (CCPs). Seems to be involved in CCPs maturation including invagination or budding. Involved in endocytosis of integrin beta-1 (ITGB1) and transferrin receptor (TFR). Plays a role in dendrite formation by melanocytes.
Synonyms: KIAA1256; SH3D1B; SWAP; SH3P18; SWA; PRO2015
Tractability: Antibody: its Gene Ontology location is reachable by antibodies, with medium confidence. PROTAC: ubiquitination databases record sites on it; its protein half-life has been measured.
Gene: Protein-coding gene on chromosome 2 (24,202,864 to 24,360,807, reverse strand). Ensembl gene ENSG00000198399.
Subcellular location: Cytoplasm
Subcellular location (Human Protein Atlas): Plasma membrane; Vesicles
Pathways (Reactome):
Vesicle-mediated transport: Cargo recognition for clathrin-mediated endocytosis; Clathrin-mediated endocytosis
Signal Transduction: RHOU GTPase cycle
Gene Ontology:
Molecular function: protein binding; protein-macromolecule adaptor activity; calcium ion binding; guanyl-nucleotide exchange factor activity
Biological process: positive regulation of dendrite extension; clathrin-dependent synaptic vesicle endocytosis
Cellular component: centrosome; extracellular exosome; cytosol; intracellular vesicle; cytoplasm; presynapse
Genetic constraint (gnomAD): Loss-of-function variants: 100 observed, 154.83 expected, observed/expected ratio (o/e) 0.65, 90% interval 0.55 to 0.76. The upper end of that interval is the gene's LOEUF score, 0.76, which puts it in group 3 of 6, group 1 being the genes least tolerant of losing a copy. Missense variants: 1,295 observed, 1,478.6 expected, observed/expected ratio (o/e) 0.88, 90% interval 0.84 to 0.92. Synonymous variants: 511 observed, 534.74 expected, observed/expected ratio (o/e) 0.96, 90% interval 0.89 to 1.03.
Homologues: Orthologues: chimpanzee ITSN2 (98% identical), macaque ITSN2 (98% identical), pig ITSN2 (95% identical), dog ITSN2 (95% identical), rat Itsn2 (93% identical), guinea pig ITSN2 (93% identical), rabbit ITSN2 (92% identical), mouse Itsn2 (92% identical), tropical clawed frog itsn2 (75% identical), zebrafish itsn2a (57% identical), zebrafish itsn2b (56% identical), Caenorhabditis elegans itsn-1 (20% identical), and 3 more. Paralogues in human: ITSN1 (60% identical), EPS15L1 (12% identical), EPS15 (11% identical), REPS1 (8% identical), REPS2 (7% identical), EHD2 (6% identical), EHD1 (6% identical), EHD3 (6% identical), EHD4 (6% identical), SRL (4% identical).
Diseases named in the same sentence as ITSN2 in open-access papers:
ITSN2 is named in the same sentence as 23 diseases in open-access papers, as found by Europe PMC text mining. Sharing a sentence is not in itself a finding about the gene and the disease. The quoted sentences say what the papers report.
viral infection (3 papers, 2018 to 2024). "The characterisation of the adaptive immune response during viral infection or immunisation highlighted that ITSN2 deletion causes severe defects in the differentiation of GC B cells and production of high affinity antibodies." (PMID 29337666, 2018). "Intersectin 2 plays important role in the regulation of the adaptive immune response in viral infection." (PMID 32526950, 2020). "These experiments show that ITSN2 plays an important role in the generation of B cell responses upon viral infection." (PMID 29337666, 2018). "In conclusion, our study not only revealed a key role for ITSN2 as an important regulator of adaptive immune-response during vaccination and viral infection but it is also likely to contribute to a better understanding of human immune pathologies." (PMID 29337666, 2018). "We found that 4 and 5 days after viral infection, Itsn2-/- mice showed significantly lower body weight than their WT counterparts." (PMID 29337666, 2018). "Hence, these results support the notion that ITSN2 is required for establishing protective immune responses against viral infection." (PMID 29337666, 2018). "To test whether Itsn2-/- B cells were also impaired in responding to viral infection, we infected 80–20 chimeras in μMT or 50–50 chimeras in B6.CD45.1 with Vaccinia virus injected intra-footpad and characterised the immune response in the draining popliteal lymph node 7 days later." (PMID 29337666, 2018). "The cytoskeleton modulator intersectin 2 (ITSN2) has GEF activity and regulates expression of SLAM, CD84, and ICOSL to promote long-term B–T cell conjugate formation, as well as GC maintenance and memory against vaccination and viral infections." (PMID 39121196, 2024).
cervical cancer (1 paper, 2021). A primary or metastatic malignant neoplasm involving the cervix.
Down syndrome (1 paper, 2013). "While this is the first study to report the differential expression of ITSN2 in replicative senescence, a recent report had implicated dysregution and overexpression of ITSN1 in Down Syndrome patients in an age-associated manner." (PMID 23472054, 2013).
Immunodeficiency (1 paper, 2018). Failure of the immune system to protect the body adequately from infection, due to the absence or insufficiency of some component process or substance. "As the results thus far were obtained with ITSN2 constitutive knockout mice, we wanted to test whether immunodeficiency presented by these animals was associated with B cell intrinsic defects." (PMID 29337666, 2018). "The strong immunodeficiency that we observed in Itsn2-/- animals raises the question of whether this molecule is required for biochemical and cellular responses downstream of the BCR." (PMID 29337666, 2018).
influenza infection (1 paper, 2018). "As a result, the survival of the ITSN2 KO animals was reduced (p=0.0345) compared to that of WT littermates upon influenza infection." (PMID 29337666, 2018).
liver cirrhosis (1 paper, 2019). "On the other hand, mutations in ITSN2 were found in tumors without vascular invasion, while mutations of ABCA2 gene were only identified in the tumors of patients without liver cirrhosis." (PMID 31429776, 2019).
lymphoma (1 paper, 2018). A malignant (clonal) proliferation of B- lymphocytes or T- lymphocytes which involves the lymph nodes, bone marrow and/or extranodal sites. "We also observed a reduction in actin foci in two independent CRISPR/Cas9 inactivated Itsn2-/- A20 lymphoma B cell lines expressing a HEL-specific BCR." (PMID 29337666, 2018).
mastitis (1 paper, 2022). Inflammation of breast tissue during lactation or postpartum due to an obstructed duct or infection. "Some positively selected genes were reported to be associated with lactation function and disease resistance, such as the butterfat rate [PPARGC1A], milk production [B4GALT1], immunity [IL2 and NFATC3], and mastitis resistance [ITSN2]." (PMID 35422847, 2022).
nephrosis (1 paper, 2018). Pathological processes of the KIDNEY without inflammatory or neoplastic components. "To test whether loss of function of ITSN1 and ITSN2 GEF activity causes a nephrosis phenotype in humans, we examined the effect of mutations identified in patients with pTSNS on the active states of Cdc42." (PMID 29773874, 2018).
osteosarcoma (1 paper, 2021). A usually aggressive malignant bone-forming mesenchymal neoplasm, predominantly affecting adolescents and young adults. "We also detected an ITSN2-ALK fusion in a patient with osteosarcoma who demonstrated poor sensitivity to alectinib." (PMID 34036223, 2021).
primary immunodeficiency (1 paper, 2018). "Interestingly, ITSN2 has been identified as a potential candidate for primary immunodeficiency in a bioinformatics screen." (PMID 29337666, 2018).
schizophrenia (1 paper, 2014). A major psychotic disorder characterized by abnormalities in the perception or expression of reality. "Another SNP in ITSN2, rs6707600 (intronic, 1000 G CEU MAF = 0.017, 89 Kb from rs2303296, r2 = 0.02), has shown some evidence of association with antipsychotic response in schizophrenia patients." (PMID 24786987, 2014).
Sjögren’s syndrome (1 paper, 2018). "Interestingly, in a large-scale association study, ITSN2 has been identified as a potential at-risk locus for Sjögren’s syndrome, a common autoimmune pathology characterised by keratoconjunctivitis and xerostomia." (PMID 29337666, 2018). "Moreover, the ITSN2 locus has been found to be differentially methylated in B lymphocytes from healthy donors versus cells from Sjögren’s syndrome patients." (PMID 29337666, 2018). "Moreover, ITSN2 was found to be overexpressed in B lymphocytes from patients with Sjögren’s syndrome." (PMID 29337666, 2018).
uveitis (1 paper, 2020). An inflammatory process affecting a part of or the entire uvea. "Cluster 3 (C3) represented a gene signature associated with uveitis that includes core B cell genes, including the MS4A1 gene (encoding CD20), Toll-Like Receptors (TLR) TLR7 and CD180 that regulates B cells responses, and ITSN2 a key gene required for antibody formation in B cells." (PMID 33042130, 2020).
tumor (4 papers, 2019 to 2025). "The first was a group of novel genes and the second was a group of genes associated with various cancer and tumour diseases (TXNDC12, NRDC, MIR761, ITSN2, NCOA1, SCUBE2, DENND5A, RCN2)." (PMID 40003092, 2025). "In addition, ALOX15B, LCN2, PRSS12, CD79B and ITSN2 showed tumor lesion-specific changes for all four patients." (PMID 37488117, 2023). "FCHSD1 may functionally cooperate with interacting genes (e.g., SBK1, ITSN2, and FNBP4) to collectively drive tumor malignancy, thus warranting further mechanistic investigations to elucidate these molecular interactions." (PMID 40535123, 2025). "FCHSD1 may functionally interact with SBK1, ITSN2, and FNBP4 to collectively regulate malignant tumor progression." (PMID 40535123, 2025).
infection (2 papers, 2013 to 2018). The state of being infected such as from the introduction of a foreign agent such as serum, vaccine, antigenic substance or organism. "We probed the function of this protein in the B cell compartment by studying ITSN2 deficient mice and mixed BM chimeras and using a combination of immunisation and infection experiments." (PMID 29337666, 2018). "We show that genetic ablation of ITSN2 rendered mice more sensitive to a lethal infection with Influenza virus." (PMID 29337666, 2018). "ITSN2 levels increased 24 h after infection with Ad-ING1a and reached maximum levels 36 h post-infection." (PMID 23472054, 2013). "Indeed, the first Itsn2-/- animals were sacrificed as early as 3 days post infection, while the majority of WT animals survived until day six post-infection." (PMID 29337666, 2018). "In this study, through a combination of immunisation and infection experiments in mice lacking ITSN2, we have provided the first analysis of the role of this adaptor protein during immune responses." (PMID 29337666, 2018).
ITSN2 also shares sentences with these, for which no sentence is quoted: breast carcinoma (1 paper); cancer (1); diabetes (1); Obesity (1); premature aging syndrome (1); pulmonary fibrosis (1); thyroid cancer (1).